EGFR (epidermal growth factor receptor)
Diseases named in the same sentence as EGFR in open-access papers (continued):
Sharing a sentence is not in itself a finding about the gene and the disease.
colon carcinoma (continued). "Also, the EGFR signalling pathway suppresses miR-143/145 in colonic cells, while overexpression of these miRNAs suppresses EGFR-induced colon cancer cell growth." (PMID 29360852, 2018). "HT could improve the effects of EGFR inhibitors acting as a useful therapeutic agent in patients with colon cancer." (PMID 30583613, 2018). "In addition, Gerwert’s group used Raman microscopy to follow the uptake of the molecular targeted agent erlotinib, an anticancer drug, to the tyrosine kinase domain of EGFR within colon cancer cells (SW480)." (PMID 29721403, 2018). "Thus, this EGFRvIII-CAR can target colon cancer cells expressing WT EGFR, albeit at a low efficiency." (PMID 29685162, 2018). "To address this, we tested whether MHYs can induce Src activation in EGFR null colon cancer cells (SW620)." (PMID 30158525, 2018). "HT may downregulate epidermal growth factor (EGFR) expression and inhibit cell cycle progression in colon cancer cells, similarly to cetuximab, a monoclonal antibody against EGFR." (PMID 30583613, 2018). "We next construct a CAR against colon cancer cells using EGFR as a target." (PMID 29685162, 2018). "As Vemurafenib treatment induces EGFR feedback activation, this may explain the refractoriness of BRAF (V600E) mutated colon cancers to this therapy." (PMID 29593231, 2018). "Interestingly, these metabolites displayed a preferential anti-proliferative effect on colon cancer cell lines with an intrinsic resistance to anti-EGFR therapies." (PMID 29593231, 2018). "Clinical biomarkers shown to be predictive of certain epithelial tumors, such as EGFR or KRAS mutations in colon cancer, are infrequent and/or not predictive of esophageal cancers." (PMID 29507700, 2018). "Moreover, we had 50 PM effusions tested for the EGFR and KRAS mutational analysis based on the previous or contemporary diagnoses of Non Small Cell Lung Cancer (NSCLC) and colon carcinomas." (PMID 28099523, 2017). "Indeed, melanoma cells with poor EGFR background are highly responsive to BRAF inhibitors, whereas colon carcinoma cells exhibit a rapid feedback activation of EGFR phosphorylation, being characterized by high EGFR expression." (PMID 29033690, 2017). "Moreover, we demonstrated that silencing FOXD3 in human colon cancer cells markedly activated EGFR/Ras/Raf/MEK/ERK signal pathway." (PMID 27926503, 2017). "Inhibition of the MET kinase activity by JNJ38877605 or inhibition of the biological activity of HGF by SRI31215, a novel small molecule inhibitor of pro-HGF activation, restored sensitivity of HGF-producing colon cancer cells to EGFR inhibition by blocking autocrine MET activation." (PMID 28420162, 2017). "Silencing FOXD3 markedly activated EGFR/Ras/Raf/MEK/ERK pathway in human colon cancer cells." (PMID 27926503, 2017). "In this study, we aimed to determine whether feedback signaling induced by EGFR inhibitors could contribute to a decreased efficacy of EGFR inhibitors in colon cancer cells." (PMID 28032592, 2017). "miR-20b reduced 5-FU resistance for apoptotic induction by inhibiting ADAM9/EGFR pathway in colon cancer cells, whereas miRNA-34c-5p inhibited amphiregulin-induced chemoresistance to docetaxel and carboplatin in ovarian cancer cells via the downregulation of AREG-EGFR pathway." (PMID 28938696, 2017). "Moreover, other reports showed that fisetin induces cell cycle arrest, apoptosis and suppress the growth of human colon cancer cells by inhibiting Wnt/EGFR/NF-kB and COX-2 signaling pathways." (PMID 28052097, 2017). "Our data provided novle molecular mechanism for further investigation if NCTD could serve as a dual inhibitor for EGFR/c-Met in terms of colon cancer treatment." (PMID 28086832, 2017). "Evidence for cooperativity was found in functional experiments when HT and cetuximab combination (10 μM and 1 μg/ml respectively), produced greater EGFR signaling impairment than that elicited by the single agents in the colon cancer cells examined (HT-29 and WiDr)." (PMID 29137335, 2017).
colon carcinoma (continued). "In sum, the polyphenol HT combined with the anti-EGFR antibody cetuximab, produces a robust inhibition of colon cancer cell growth, a remarkable effect that occurs at concentrations of each agent representing a fraction (approx. 1/10) of that producing near maximal effect as single molecules." (PMID 29137335, 2017). "Therefore, it is highly desirable to find dual inhibitor for both EGFR and c-Met, especially from the existing drugs, to facilitate colon cancer treatment." (PMID 28086832, 2017). "Both types of cells expressed EGFR and neither type harboured mutations in signalling molecules downstream of EGFR that have been reported in cetuximab-resistant colon cancer patients." (PMID 27399917, 2016). "Dsg2 depletion in SK-CO15 colon cancer cells also disrupts EGFR signaling." (PMID 26918609, 2016). "This study demonstrates that the inhibition of the SOCE-dependent colon cancer cell migration trough SK3/TRPC1/Orai1 channel complex by the alkyl-lipid Ohmline may be a novel strategy to modulate Anti-EGFR mAb action in mCRC." (PMID 27102434, 2016). "We have shown that SRI 31215 blocks signaling between colon cancer cells and fibroblasts, prevents fibroblast-dependent growth and migration of cancer cells and overcomes fibroblast-induced resistance to inhibitors of EGFR." (PMID 27121052, 2016). "Furthermore, we demonstrated that SRI 31215 overcomes fibroblast-mediated resistance to EGFR inhibitors in colon cancer cells." (PMID 27121052, 2016). "Inhibition of EGFR signals in human colon cancer also influences cytokine secretion." (PMID 27683110, 2016). "The employment of a K-RAS downstream MEK inhibitor could be the key to overcome the resistance to anti-EGFR therapies, as demonstrated in lung ad colon cancer." (PMID 27429047, 2016). "Furthermore we assessed the role of the alkyl-lipid Ohmline, previously identified through its SK3/Orai1 complex inhibition properties, to modify the actions of anti-EGFR mAbs such as cetuximab and panitumumab currently used in colon cancer therapeutic." (PMID 27102434, 2016). "The unveiled promotion of a surrounding microenvironment enriched in pro-inflammatory cytokines capable of impairing the cetuximab response in otherwise sensitive cells, certainly represents an emerging link between EGFR and cytokine signalling in colon cancer." (PMID 27708224, 2016). "In addition, our study indicates that dual inhibition of HGF and EGFR precludes primary and acquired, fibroblast-mediated, resistance to EGFRi in colon cancer cells." (PMID 27121052, 2016). "Elevated levels of EGFR or increased expression levels of the EGFR gene have been reported in a number of human cancers of epithelial origin, including head and neck, thyroid, breast, and colon cancers." (PMID 27119071, 2016). "Berberine has been proven to inhibit EGFR through activation of Cbl in colon tumor cells." (PMID 27738318, 2016). "Moreover, cell line experiments revealed that B4GALNT3 expression regulates cancer stemness and the invasive properties of colon cancer cells through modifying epidermal growth factor receptor (EGFR) glycosylation and downstream signaling." (PMID 27686492, 2016). "For this reason, colon tumors harboring activating RAS mutations do not respond to EGFR targeting and mutational screening is therefore routinely used for patient selection prior to treatment." (PMID 27119512, 2016). "The EGFR signaling pathway plays a crucial role in colon cancer survival, growth, and metastasis." (PMID 27683110, 2016). "Curcumin can also inhibit the expression of EGFR in human colon cancer cells." (PMID 27831561, 2016). "Taken together, these results suggest that EGFR signaling activity in colon cancer cells might promote the polarization of M1-like macrophages into M2-like macrophages." (PMID 27683110, 2016). "Cetuximab might inhibit EGFR signaling in colon cancer cells and alter the secretion of other factors into the tumor microenvironment, consequently preventing macrophage polarization." (PMID 27683110, 2016).
colon carcinoma (continued). "In a reciprocal manner, EGFR inhibition is effective in most epithelial cancers with EGFR mutations, but molecular alterations of KRAS have been implicated in acquired resistance to anti-EGFR therapies in colon cancer patients." (PMID 26916442, 2016). "Modern treatment strategies of cancer diseases aim at efficaciously modulating specific signaling and transcriptional pathways (for instance, VEGF antibodies, tyrosine kinase inhibitors for treating chronic lymphatic leukemia, or EGFR antibodies for treating advanced colon carcinoma)." (PMID 26219286, 2015). "Moreover, the authors showed that forced expression of MITF reduced EGFR signaling in melanoma and colon cancer cells, which restored sensitivity to BRAFi/MEKi." (PMID 26393652, 2015). "Using vemurafenib to target colon cancer patients with the same BRAFV600E mutation has shown poor efficacy, which may be due to rapid feedback activation of EGFR." (PMID 26525348, 2015). "The miRNAs that target EGFR signaling pathway in colon cancers have been well documented." (PMID 26064956, 2015). "Therefore, there is a high degree of expectation in combination therapy of BRAF inhibitor and anti-EGFR antigen, etc. for BRAF mutation-positive colon cancer, and the outcome of future clinical trials is eagerly expected." (PMID 25936694, 2015). "For instance, melanoma and colon cancer patients harboring the same BRAF (V600E) mutation respond differently to BRAF inhibitors because colon cancer cells but not melanoma cells gain feedback activation of EGFR and its signaling pathway." (PMID 26220863, 2015). "Both colon tumor epithelial cells and TAFs share EGFR expression." (PMID 25987127, 2015). "Feedback loops that involve specific miRNAs and different components of the EGFR pathway also exist: miR-143 and miR-145 regulate the EGFR pathway genes KRAS, BRAF, and MEK2, but EGFR signals down-regulated these tumor suppressor miRNAs in a murine model of colon cancer." (PMID 26287249, 2015). "Anti-EGFR antibody, cetuximab or panitumumab is a treatment for colon cancer that is highly effective to patients with expression of EGFR protein; however, it has been reported that patients with KRAS gene mutations that lie downstream acquire resistance against therapy." (PMID 25936694, 2015). "In addition, some preclinical studies suggest that cetuximab inhibits the proliferation of colon cancer cell lines expressing EGFR and enhances the antitumor activity of chemotherapy and radiotherapy." (PMID 26491668, 2015). "EGFR has been a therapeutic target in a range of tumors including colon cancer." (PMID 26064956, 2015). "Therefore, the observed anti-EGFR activity of AEE788 in colon cancer cells is strongly dependent on wild-type K-Ras status." (PMID 26107817, 2015). "In addition, studies using human colon cancer cell lines showed that AhR activation in vitro increases cell proliferation, migration, and invasion via transactivation of the EGFR/ERK signaling pathway." (PMID 26264025, 2015). "Our result showed that B4GALNT3 knockdown reduced LacdiNAc structure on EGFR in colon cancer cells." (PMID 25003232, 2014). "Interestingly, considering the cut-off values of 5% and 10% positive tumour cells, we found the co-expression of EGFR/HER-4 to be significantly associated with disease-free survival in patients with Dukes’ C and D colon cancer in this study." (PMID 24609222, 2014). "Similarly, PCR for GA733-2, CEA, and epidermal growth factor receptor (EGFR) is performed to diagnose colon cancer and PCR for PSMA, PSA, and EGFR to diagnose prostate cancer." (PMID 25258614, 2014). "They showed that the expression of Spry2 positively correlates with the sensitivity of colon cancer cells to the EGFR inhibitor gefitinib and that Spry2 can enhance the response of colon cancer cells to gefitinib by increasing the expression of phosphorylated EGFR, total EGFR, and PTEN." (PMID 24744103, 2014).
colon carcinoma (continued). "Prior study also proposed that both enhanced SRC activity and EGFR phosphorylation at Y845 could be a potential mechanism of cetuximab resistance in colon cancer." (PMID 25301722, 2014). "We therefore investigated whether B4GALNT3 could regulate stem-like potential of colon cancer cells via the EGF/EGFR pathway." (PMID 25003232, 2014). "REG4 protein also transactivates EGFR signaling and reduces apoptosis in colon cancer cells." (PMID 24533081, 2014). "Our results strongly imply PTPRO in negative regulation of EGFR signaling, suggesting that PTPRO expression could affect the sensitivity of colon cancer cells to EGFR inhibitors." (PMID 25301722, 2014). "Furthermore, berberine stimulated Cbl activation, which mediated down-regulation of EGFR and inhibition of cell proliferation in mouse and human colon tumor cells." (PMID 23457600, 2013). "Mutations of the KRAS gene are known to be negative predictive genetic markers for EGFR targeted therapy and were significantly associated with resistance to EGFR-blocking monoclonal antibody (cetuximab) in colon cancer." (PMID 24205362, 2013). "Measurements of EGFR expressed on human colon cancer cells in vitro indicate that metastatic cells may express as much as five-times more EGFR in comparison to nonmetastatic cells." (PMID 23986907, 2013). "However, in some studies specifically of colon cancer, EGFR expression correlated with poor prognosis." (PMID 24204699, 2013). "Furthermore, in another published work, it was demonstrated that EGFR suppress miR-143 and miR-145 in a murine models of colon cancer." (PMID 24040120, 2013). "In a subanalysis including only colon cancer, our study showed an association between EGFR expression and improved survival, but the difference was not significant (data not shown)." (PMID 24204699, 2013). "Therefore, enhancing EGFR degradation is a potential mechanism by which berberine inhibits EGFR's function in colon tumor cells." (PMID 23457600, 2013). "Also, EGFR expression and tyrosine kinase activity are upregulated in metastatic colon cancer cells." (PMID 24276379, 2013). "Blockade of EGFR signaling significantly inhibits tumor growth in animal models of colon cancer." (PMID 23900414, 2013). "To determine the effects of berberine on regulation of EGFR activity in colon cancer cells, we chose two colonic tumor cell lines, the immorto Min mouse colonic epithelial (IMCE) cells carrying the APCmin mutation, and HT-29 cells which were isolated from human colonic carcinoma." (PMID 23457600, 2013). "Immunohistochemical studies on human colon cancer specimens revealed inter- and intratumoral heterogeneity for the expression of different receptor tyrosine kinases (RTKs), including EGFR, vascular endothelial growth factor receptor-2 (VEGFR2), and platelet-derived growth factor receptor β (PDGFRβ)." (PMID 23900414, 2013). "Anti-EGFR treatments that have been developed for colon cancer are promising." (PMID 23459231, 2013). "Our group has been exploring the over-the-counter laxative polyethylene glycol (PEG) for its remarkable potency at downregulating EGFR and thus providing a potential explanation for its colon cancer chemopreventive efficacy (documented by several groups in a number of pre-clinical models)." (PMID 22675506, 2012). "For instance, Cld2 expressed in certain colon cancer cells played a significant role in their epidermal growth factor receptor (EGFR)-mediated cell proliferation, inasmuch as the knockdown of endogenous Cldn2 compromised proliferation in vitro and tumorigenesis in vivo." (PMID 23284964, 2012). "Reg IV is a potent activator of the epidermal growth factor receptor (EGFR)/Akt/activator protein-1 (AP-1) signaling pathway in colon cancer cells and increases expression of Bcl-2, Bcl-xl and survivin, which are proteins associated with the inhibition of apoptosis." (PMID 23133598, 2012).
colon carcinoma (continued). "Importantly, the integral nature of EGFR was shown by the demonstration that EGFR knockdown (via shRNA) blunted the chemopreventive efficacy of PEG in this model of colon cancer." (PMID 22675506, 2012). "Although not examined in this study, such drug combinations may be of therapeutic interest also for other tumor entities characterized by therapy resistance and EGFR overexpression, such as colon cancer." (PMID 22289787, 2012). "The signalling by EGFR-ErbB3 heterodimers may play an important role in colon cancer cell lines; in fact, inhibition of AKT phosphorylation and cell proliferation by the EGFR-specific inhibitor erlotinib (Tarceva) correlated with expression of ErbB3." (PMID 22889873, 2012). "Additionally, overexpression of EGFR has been reported in up to 85% of human colon cancers, and expression of EGFR in colon cancer is correlated with a more aggressive disease and poor patient prognosis." (PMID 22761867, 2012). "Therefore, only biopsy of lung lesion allowed the diagnosis of EGFR positive colon carcinoma metastases." (PMID 21627796, 2011). "Finally, only a percutaneous transthoracic needle aspiration biopsy of the unmodified nodules allowed the diagnosis of EGFR positive colon carcinoma metastases." (PMID 21627796, 2011). "Cox-2 is an EGFR effector in this model that suppresses apoptosis in colon cancer cells." (PMID 22070864, 2011). "In addition, the expression of SGLT1, an active glucose transporterwhich is stabilized by EGFR, was also decreased by HDACi and led to the reduction ofglucose uptake in colon cancer cells." (PMID 21464950, 2011). "In wild-type KRAS colon cancer, EGFR amplification has also been reported as a predictive marker." (PMID 24212636, 2011). "5-FU or GEM were able to synergistically enhance antibody dependent cell-mediated cytotoxic (ADCC) mediated killing of colon cancer cell lines by cetuximab (a monoclonal antibody targeting epidermal growth receptor, EGFR) by increasing expression of EGFR on tumors." (PMID 24212948, 2011). "Moreover, knockdown of Sp1, Sp3 and Sp4 (in combination) in RKO colon cancer cells also decreased expression of EGFR, cyclin D1, p65 and PTTG-1, confirming the role of Sp transcription factors in regulating expression of these genes." (PMID 21864401, 2011). "Furthermore, in the colon cancer xenograft model, inhibitors of EGFR and Src dramatically blocked the tumor formation promoted by nicotine injection." (PMID 22085699, 2011). "We detected membranous EGFR expression using the EGFR pharmDx kit in 214 (59%) colon carcinomas." (PMID 19997103, 2010). "Evidence suggests that epidermal growth factor receptor (EGFR)-activation status may better predict the clinical behaviour of colon cancers than does EGFR expression." (PMID 19997103, 2010). "Phospho-EGFR (Tyr-1173) expression was detected in 157 of 388 (40%) colon cancers." (PMID 19997103, 2010). "Epidermal growth factor receptor (EGFR) was reported to be overexpressed in colon cancer." (PMID 23554613, 2010). "In NSCLC and colon cancers a positive association between EGFR gene amplification and protein expression has also not been consistently observed." (PMID 19636423, 2009). "In other cancer subtypes such as colon cancers EGFR-targeting agents also show clinical efficacy." (PMID 17667926, 2007). "This redistribution of EGFR to apical plasma membranes in advanced colon carcinoma cells suggests that autocrine growth factors in the colon lumen may play a significant role during tumour progression." (PMID 9667648, 1998). "Consequently, we hypothesized that SLC5A1 may regulate the EGFR phosphorylation level, thereby influencing the proliferation, migration, and invasion of colon cancer." (PMID 39781340, 2025).